FAP (fibroblast activation protein alpha)
Diseases named in the same sentence as FAP in open-access papers (continued):
Sharing a sentence is not in itself a finding about the gene and the disease.
tumor (continued). "FAP is a serine protease that is not expressed in normal adult tissues, but its expression is induced in activated fibroblasts responding to wound healing and tumor-stroma reaction." (PMID 19721715, 2009). "Consequently, a surgical guidance technique based on FAP expression in the peritumoral stroma, rather than on a cancer cell-specific marker, may better consider the full extent of the tumor, minimizing postoperative malignant residues." (PMID 41258458, 2025). "Indeed, rather than viewing FAP expression as a surrogate marker, its presence might directly influence tumor behavior through mechanisms that facilitate tumor growth and tissue infiltration." (PMID 41303595, 2025). "While FAP is highly expressed in fibroblasts within fibrotic lesions and tumors, its reduced levels in aggressive lymphoid malignancies suggest it may reflect a systemic reaction to the tumor rather than being tumor-derived." (PMID 41373408, 2025). "Therefore, we postulated that CAFs positive for FAP in combination with any other marker but negative for COL1A1 might be a tumor‐promoting myCAF population." (PMID 39563958, 2024). "Counts of FAP− U251 cells were reduced significantly only when co‐cultured with both U87 cells and FAP‐CAR‐T cells, suggesting that antigen‐negative U251 tumor cells are also susceptible to bystander killing from FAP‐CAR‐T cells, similar to our earlier observations using GNS cells." (PMID 38975278, 2024). "FAP also has nonenzymatic catalytic activity and exerts effects such as promoting the proliferation of tumor cells, degrading and reconstructing the extracellular matrix, establishing the tumor vasculature, and mediating the immunosuppressive tumor environment." (PMID 38740736, 2024). "However, this strategy might not be viable in tumors where FAP+ CAFs are situated at a greater distance from tumor cells." (PMID 38540204, 2024). "Additionally, FGF21 may be inactivated by cleavage by Fibroblast Activation Protein (FAP), affecting GBM cell metabolic regulation and tumor progression, This aligns with our findings that FGF21 may mediate the causal relationship between PC16 and GBM as an intermediary factor." (PMID 39286013, 2024). "In addition, the modification of FAP aptamers on the surface of immune cells can reduce interference to the inherent anti-tumor biological functions of immune cells, and as a non-genetic approach, it also has the advantages of flexibility, controllability, and predictability." (PMID 36838669, 2023). "However, the relationship between FAP expression and tumor location has not been investigated." (PMID 37316886, 2023). "Also, FAP-negative HT-1080 tumor-bearing mice revealed low tumor uptake." (PMID 36864362, 2023). "In addition, with higher lipophilicity than that of DOTA or NOTA conjugates, the accumulation of [18F]3 in the urinary system may be lower than that of a previously reported chelator containing FAP PET tracer, implying a higher tumor-to-background ratio in the urinary system." (PMID 37057133, 2023). "However, the available evidence has shown that FAPI is not an entirely tumour-specific agent, possibly due to a fibrotic reaction and FAP activation in chronic inflammation, increased radiolabeled FAPI uptake has been demonstrated in non-malignant conditions in recent studies." (PMID 37608378, 2023). "Furthermore, this study did not explore whether HHLA2 and FAP jointly or separately increase or decrease the anti-tumor immune response or the mechanism involved, and this should be investigated further." (PMID 36598731, 2023).
tumor (continued). "Therefore, this difference in differentiation and the overall DSR of the tumor is much better reflected by an absolute FAP quantification of protein or gene expression level than by the number of FAP-positive fibroblasts, independent of their staining intensity." (PMID 37569808, 2023). "Interestingly, we observed that FAP-targeted CAR-T cells could suppress the recruitment of myeloid-derived suppressor cells (MDSCs) and promote the survival of CD8+ T cells and CAR-T cells in tumor tissue." (PMID 37046312, 2023). "Interestingly, contrary to the better in vitro FAP-inhibitory performance of natGa-SB03058 than natGa-FAPI-04, its radioactive equivalent [68Ga]Ga-SB03058 (7.93 ± 1.33 %ID/g) demonstrated a ~1.5 fold lower tumor uptake than that of [68Ga]Ga-FAPI-04 (11.9 ± 2.17 %ID/g)." (PMID 37110717, 2023). "Results showed that conditioned medium from FAP-over-expressed LX2 cells could decrease the expression of M1 markers like iNOS, TNF-α and IL-1β but increase the expression of M2 markers like IL-10 in macrophages as compared to NC group, transforming the macrophages into M2 pro-tumor phenotype." (PMID 37325617, 2023). "Finally, FAP NPs with an α-disulfide bond showed more-potent antitumor effects than FBP NPs and FGP NPs, which could be ascribed to higher reduction-responsiveness and faster tumor-specific drug release." (PMID 36986645, 2023). "In addition, FGF2 and p-FGFR1 were highly expressed in FAPα+ HSCs in the co-opted sinusoidal blood vessels in bevacizumab-resistant HCT116 and HT-29 CRCLM xenografts, indicating that tumor cell–derived FGFBP1 might induce FAPα expression in HSCs by activating the FGF2/FGFR1 signaling pathway." (PMID 35951441, 2022). "However, the authors could not evaluated the on-target/off-tumor toxicity of their CAR-T cells since F19-FAP antibody targets only the human version of FAP, with no cross-reactivity with the mouse version." (PMID 35211124, 2022). "Interestingly, in contrast to the tumor tissue, we could not detect any FAP mRNA by the GD2-positive murine NB cells NXS2-HGW that served for tumor establishment in vivo." (PMID 36230765, 2022). "However, the findings of a further study have indicated that the presence of highly reactive FAP-specific CAR-modified T cells can promote severe cachexia and dose-limiting bone toxicity without significantly affecting tumor suppression among different syngeneic tumor implantation models in mice." (PMID 36263225, 2022). "Because FAP+ fibroblasts and SPP1+ macrophages were closely involved in the hypoxia-induced pathway, we hypothesized the presence of a stromal cell-mediated network localized in the hypoxic region of the tumor that links macrophages and MSCs, which collaborate to exacerbate the CRC microenvironment." (PMID 35365629, 2022). "Given that FAPα expression in CAFs can enhance the infiltration of MDSCs, impair antitumor T cell immunity, and promote tumor cell EMT, we speculated that FAPα+ HSCs may preestablish an immunosuppressive niche and induce tumor cell EMT to promote vessel co-option." (PMID 35951441, 2022). "FAP has been targeted in tumors for imaging and therapy using several approaches, including immunoconjugates (an antibody–maytansinoid conjugate (mAb FAP5-DM1)), CAR T cells, tumor immunotherapy, vaccines, peptide drug complexes, FAP inhibitors, and antibodies." (PMID 35326670, 2022). "Thus, FAP can induce tumor growth and extracellular matrix degradation, regardless of whether it has high or low enzymatic activity." (PMID 34490078, 2021). "Thus, targeting FAP+ stromal cells with CAR T-cells can greatly broaden the application of this therapy, and we hypothesize that using CAR T-cells to selectively eliminate FAP+ cells may improve patient survival, given the tumor-promoting effects of FAP+ CAFs." (PMID 34490078, 2021).
tumor (continued). "Although tumor stromal fibroblasts in general may express α-SMA, FAP, vimentin, neuron-glial antigen-2 (NG2) chondroitin sulfate proteoglycan, PDGFRβ, prolyl 4-hydroxylase and FSP1; α-SMA and FAP can be used to discriminate myofibroblasts form fibroblasts in the tumor tissue." (PMID 34336660, 2021). "The identity of this latter FAP+ perivascular population is presently unclear and could include classical pericytes, mesenchymal stem/stromal cells (MSC), perivascular macrophages or a subpopulation of tumor cells (possibly stem‐like cells) residing in the perivascular niche." (PMID 33082953, 2020). "Having established that the FAP+ HO-1+ TAM phenotype was regulated by IL-6 signalling, we next considered whether these cells might also populate specific anatomical locations within the 4T1 tumour, and discovered a tendency for these cells to accumulate around viable vasculature." (PMID 30054470, 2018). "In conclusion, we have generated bispecific agonist CD40/FAP DARPin® molecules able to activate the CD40 pathway in cellular assays in a targeting-dependent manner, supporting the hypothesis that these DARPin® molecules could lead to a tumor-localized immune activation in vivo." (PMID 30400822, 2018). "Importantly, HLA-A*02:01/NY-ESO-1157-165 peptide-specific re-directed T cells could not control the growth of FAP + tumor cells demonstrating the antigen-specific therapeutic effect of our re-directed FAP-specific T cells." (PMID 23937772, 2013). "Signs of biological activity observed in peripheral blood did not translate into meaningful changes in the tumor microenvironment, and the low clinical activity indicates that resistance to PD-1 CPI cannot be overcome by the addition of FAP-IL2v." (PMID 39895413, 2025). "However, a prolonged circulation time of FAP-targeting antibodies and limited tumor retention were reported, since the radioligand binds to fibroblasts in the tumor microenvironment rather than to tumor cells themselves, in contrast to radioligand therapy with prostate-specific membrane antigens." (PMID 40647503, 2025). "A critical limitation in this field is the lack of truly tumor‐specific CAF markers, as most targets (e.g., FAP, α‐SMA) are also expressed in physiologic wound healing or normal stromal compartments." (PMID 41164803, 2025). "Although 177Lu-FAP-2286 did not exhibit the best tumor uptake in HT1080.hFAP tumor models, it demonstrated optimal tumor uptake and biodistribution in HEK293.hFAP tumor models." (PMID 40438601, 2025). "Remarkably, 68Ga-FAP-2286 exhibited the same rapid renal clearance as 68Ga-FAPI-46, with no noticeable differences in tumor distribution between the two tracers." (PMID 38543239, 2024). "Tumor PET accumulation was significantly greater in the MDA-MB-231 than in the HT1080 xenografts, where the latter were used as an FAP negative control." (PMID 39519118, 2024). "In HCC ST slides from immunotherapy-non-responsive patients, FAP and DAB2 were found to be concentrated at the tumor border, creating a barrier that effectively blocked the infiltration of T/B cells." (PMID 39239526, 2024). "Fibroblast activation markers FAP, CD29, αSMA, PDPN, CD90, FSP1 and PDGFRβ expression levels were determined and compared for tumour and non-cancerous adjacent lung tissue from NSCLC patients by looking at the percentage positivity for each marker." (PMID 38582812, 2024). "In FAP-negative 4T1 and Panc02 allografted models, infused FAP-CAR T cells can only recognize and therefore lyse tumor stromal fibroblasts to slow the tumor progression, proving deletion of CAFs a valuable tumor therapeutic approach." (PMID 39086477, 2024). "We observed that treatment with Ro5‐3335 effectively blocked LLC tumor progression via inhibiting CAF formation (α‐SMA and FAP) in vivo, without any observed adverse effects." (PMID 37967345, 2024).
tumor (continued). "Sibrotuzumab, which is the first anti-FAP humanized monoclonal antibody, was developed as a CAF-targeted therapy to suppress tumor progression, however, this therapy has not yet shown clinical efficacy." (PMID 38555315, 2024). "It was found that only 6 hours after co-culture with FAP-CAR T cells, hFAP-HT1080 cells lost parts of their surface FAP expression (data not shown), in line with recent reports that tumor cells decreased their target density after contact with CARTs." (PMID 39086477, 2024). "Administration of an anti-FAP monoclonal antibody (mAb), FAP5-DM, has provided long-lasting inhibition of tumor growth and even complete tumor regression with no signs of intolerability in stroma-rich xenograft models of various cancers." (PMID 37784082, 2023). "In multifactorial analysis, only tumor site, Snail1, and N-cadherin were independent prognostic prognostic factors, while TRG grading, CAF marker FAP and CD10 were not." (PMID 37277751, 2023). "To investigate this, we segregated the data population based on the expression of CD105, FAP and FSP mRNA and the absence of CD34 mRNA expression, considering that the data from these databases includes the entire tumor." (PMID 37719885, 2023). "At the mRNA level, we found that α-SMA and FAP, as well as ITGA5, were significantly upregulated in HMFs activated by TGFβ or tumor cell conditioned medium compared to non-activated HMFs and cancer cells, in which these markers were absent." (PMID 36831470, 2023). "SPECT/CT imaging showed that U87MG tumor was distinguishable and of a high uptake of 99mTc-HYNIC-FAPI-04 (2.67 ± 0.35 %ID/mL at 1.5 h post injection (h P.I.), while tumor signal of FAP-negative HUH-7 was as low as 0.34 ± 0.06 %ID/mL." (PMID 36986521, 2023). "This strategy is therefore not limited to a specific tumor antigen expressing cancer type and does not require to develop multiple Dual CAR T-cell products for different antigen combinations with FAP." (PMID 37251405, 2023). "The pharmacodynamic effects of FAP-IL2v-mediated immunotherapy, assessed by PET and immunofluorescence, were observed even in the absence of tumor shrinkage." (PMID 35874707, 2022). "In a preclinical research, FAP-specific chimeric antigen receptor T (CAR-T) cells were designed to deplete FAP+ CAFs, showing anti-tumour function without significant toxicity." (PMID 36284087, 2022). "B16-FAP tumors were clearly detected with [68Ga]Ga-DOTA-Siglec-9 PET/CT during the follow-up period, without differences in tumor volume between FAP-IL2v-treated and vehicle-treated groups." (PMID 35874707, 2022). "Normal adult tissues are generally negative for FAP, which exhibits both protease and collagenase activity and is important for extracellular matrix (ECM) degradation in wound healing and tumor invasion." (PMID 36092734, 2022). "Using our established pipeline, we designed and characterized a TCE that recognizes murine FAP that is not expressed by MC38 cells in vitro, but is abundantly expressed by the stromal cells in the TME of MC38 tumours in vivo." (PMID 36405739, 2022). "The serial SPECT/CT imaging studies in animals-bearing U87MG (FAP positive) and PC3 (FAP negative) tumors showed that the uptake of [111In]In-QCP02 in U87MG tumor was 4-fold higher than the PC3 tumor at 1 h post-injection." (PMID 34681246, 2021). "Another study showed anti-tumor efficacy and no side effects in an immunodeficient mouse model of lung cancer, while the final study, done in a mesothelioma model, showed survival benefits for tumor-bearing mice, but toxicities could not be evaluated, as the antibody did not react with mouse FAP." (PMID 34200702, 2021). "In contrast, the PSA-, hK2-, and FAP-based TG prodrugs at their ten-fold lower MTD (i.e., ~4 μmoles/kg/dose) stop tumor growth, but do not produce tumor regression." (PMID 34946547, 2021).
tumor (continued). "In contrast to FAP+ cells and THY1+ cells, the overall percentages of NT5E+ cells, TNC+ cells, and PDGFRβ+ cells were not altered in the tumor microenvironment compared to benign prostate stroma." (PMID 33600062, 2021). "The markers for GC cells, CEA and CK-18, were not expressed in NFs and CAFs, and tumor cells (TCs) do not contain α-SMA, FAP and FSP1." (PMID 32106859, 2020). "FAP expression was most prominent amongst ECs and pericytes, with lower expression on CD90+ tumor cells, and no detectable expression on CD90– tumor cells, GAMs or T cells." (PMID 33082953, 2020). "Of these mRNAs, the ADAM23, FAP, GPMNB and PRSS3 were found in the tumour-derived endothelium, but no expression was observed in tumour cells." (PMID 30189837, 2018). "FAPα immunoreactivity was observed at varied levels in the stroma of ESCC tissues, but no FAPα immunostaining presented in epithelium of tumour tissues." (PMID 28415791, 2017). "T cells are absent from regions of the tumor containing cancer cells, which are coated with the chemokine, CXCL12, and the FAP α+ CAFs are the principal source of CXCL12 in the tumor." (PMID 26985769, 2016). "Activated fibroblasts in tumor tissues are considered CAFs, and our results are consistent with the identification of activated H-CAFs as these cells expressed α-SMA and FAP, whereas NSFs expressed neither of these two markers." (PMID 23667593, 2013). "First, expression of FAP and DPP-IV is clearly independent of the malignant potential of the tumours." (PMID 19817894, 2009). "Conversely, FAP displayed a weak to moderate negative correlation (−0.3 < r < 0, p < 0.05) with tumor suppressor genes, like PTEN and CDK inhibitors (e.g., CDKN1A), hinting at its potential role in driving tumor progression." (PMID 40430845, 2025). "However, we did not observe a correlation between FAP + and CD20 + cells (tumor center, Spearman’s Rho = 0.11, p = 0.31; tumor periphery, Spearman’s Rho = 0.03; p = 0.8)." (PMID 39751643, 2025). "Furthermore, higher ES between tumour cells and CD31+ endothelial cells and FAP+ fibroblasts were discerned in cases with GCPM than without, indicating closer spatial location among them." (PMID 39422697, 2024). "In this study we demonstrated that murine FAP-targeted NIR-PIT could selectively deplete CAFs without damaging adjacent normal cells and suppress tumor growth in a CAF-rich tumor model." (PMID 38555315, 2024). "Building off the 6-methoxy modification, the investigators utilized a linkage at that position to connect the pharmacophore for FAP to DOTA for the chelation of a radiometal/metal, either 68Ga or [18F]AlF, with the choice not affecting tumor uptake in xenograft models." (PMID 39065684, 2024). "Fibroblast activation protein (FAP) targeted RPT could deliver radiation dose to CAFs, not only killing CAFs and adjacent TNBC tumor cells, but also reducing the secretion of CXCL12 by CAFs." (PMID 38587644, 2024). "In our study, FAP-CAR T cells could not eliminate tumors totally and only inhibit tumor growth in a limited period." (PMID 39086477, 2024). "Moreover, FAP was expressed in the tumor stroma of the majority (98.3%, 57 of 58 patients) of CCA, independent of patient clinical or tumor characteristics." (PMID 39664608, 2024). "The results indicate that FAP+ CAF may contribute to immune cell exclusion 60, 61 as T/B cells were often absent from the tumor core." (PMID 39239526, 2024). "Radiopharmaceuticals based on the highly potent FAP inhibitor (FAPi) UAMC-1110 have shown great potential in molecular imaging, but the short tumor retention time of the monomers do not match the physical half-lives of the important therapeutic radionuclides 177Lu and 225Ac." (PMID 36980775, 2023).